LINC02372 (long independently transcribed non-coding RNA 2372)
Gene: Long non-coding RNA gene on chromosome 12 (126,869,010 to 126,874,727, reverse strand). Ensembl gene ENSG00000249873.
Diseases named in the same sentence as LINC02372 in open-access papers:
LINC02372 is named in the same sentence as 1 disease in open-access papers, as found by Europe PMC text mining. Sharing a sentence is not in itself a finding about the gene and the disease.
LINC02372 shares sentences with these, for which no sentence is quoted: gout (1 paper).